OR2L5 (olfactory receptor family 2 subfamily L member 5)
Description:
Odorant receptor.
Synonyms: OR2L11; OR2L5P
Tractability: Antibody: UniProt places it where antibodies can reach, with medium confidence; UniProt predicts a signal peptide or a membrane-spanning region; its Gene Ontology location is reachable by antibodies, with medium confidence.
Gene: Protein-coding gene on chromosome 1 (248,013,660 to 248,024,276, forward strand). Ensembl gene ENSG00000197454.
Subcellular location: Cell membrane
Pathways (Reactome):
Sensory Perception: Expression and translocation of olfactory receptors
Gene Ontology:
Molecular function: olfactory receptor activity; G protein-coupled receptor activity
Biological process: detection of chemical stimulus involved in sensory perception of smell; G protein-coupled receptor signaling pathway
Cellular component: plasma membrane; membrane
Genetic constraint (gnomAD): Loss-of-function variants: 1 observed, 0.35 expected, observed/expected ratio (o/e) 2.85. That is too few expected variants to judge how well the gene tolerates losing a copy. Missense variants: 413 observed, 393.56 expected, observed/expected ratio (o/e) 1.05, 90% interval 0.97 to 1.14. Synonymous variants: 169 observed, 146.76 expected, observed/expected ratio (o/e) 1.15, 90% interval 1.01 to 1.31.
Homologues: Orthologues: chimpanzee OR2L5 (97% identical), macaque OR2L5 (94% identical), dog OR2L5 (84% identical), dog OR2L3B (82% identical), dog OR2L3 (82% identical), dog OR2L5C (82% identical), mouse Or2l5 (80% identical), rat Or2l5 (80% identical), dog OR2L17 (79% identical). Paralogues in human: OR2L2 (90% identical), OR2L3 (88% identical), OR2L8 (88% identical), OR2L13 (71% identical), OR2AK2 (55% identical), OR2AJ1 (53% identical), OR2M2 (52% identical), OR2M3 (52% identical), OR2M5 (51% identical), OR2T27 (51% identical), OR2T1 (51% identical), OR2M7 (50% identical), and 80 more.
Diseases named in the same sentence as OR2L5 in open-access papers:
OR2L5 is named in the same sentence as 2 diseases in open-access papers, as found by Europe PMC text mining. Sharing a sentence is not in itself a finding about the gene and the disease.
OR2L5 shares sentences with these, for which no sentence is quoted: bladder (1 paper); signet ring cell carcinoma (1).